BRAF (B-Raf proto-oncogene, serine/threonine kinase)
Diseases named in the same sentence as BRAF in open-access papers (continued):
Sharing a sentence is not in itself a finding about the gene and the disease.
thyroid tumor (continued). "BRAF V600E mutation prevalence in various thyroid neoplasms." (PMID 16606457, 2006). "Activated proto-oncogenes, such as RET/PTC, RAS, and BRAF, in thyroid tumors can trigger mitogen-activated protein kinase (MAPK) cascades, thereby promoting the spontaneous transformation of cells into a proinflammatory phenotype." (PMID 40490818, 2025). "Mutations occurring at the codons 600 of BRAF and 61 of RAS genes are common in human thyroid tumors, with these mutations being the most frequent events that lead to the activation of MAPK- and mTOR-signaling pathways." (PMID 40711277, 2025). "Thyroid neoplasms are often associated with the mutations of RET/PTC, RAS, BRAF and PTEN which is quantitatively consistent with our model." (PMID 40720480, 2025). "BRAF inhibitors, such as vemurafenib and dabrafenib, have shown potential in treating BRAF-mutant thyroid tumors." (PMID 38501105, 2024). "Our study supports further clinical evaluation of CDK4/6i and their combination with anti-BRAF/MEK therapies as a novel effective treatment against advanced thyroid tumors." (PMID 37964967, 2023). "BRAF positive thyroid tumors have shown sensitivity to RAF and/or MEK inhibitors and RET variants correlate with aggressive phenotype and worse outcome." (PMID 37483495, 2023). "These contradicting findings are also of great interest for thyroid tumors, as the status of TERT promoter mutations together with BRAF mutations have been shown to be associated with clinicopathological aggressiveness." (PMID 37418389, 2023). "Tumour cell load determination, immunological markers, circulating levels of BRAF V600E, and galectin were the most promising biomarkers for thyroid neoplasms diagnosis." (PMID 37547301, 2023). "To conclude, our study supports the potentially favorable clinical impact of CDK4/6i for the treatment of aggressive dedifferentiated thyroid tumors including in combinations with anti-BRAF/MEK and, likely, anti-ERK therapies." (PMID 37964967, 2023). "The study aimed to evaluate BRAF expression in differentiated thyroid tumors with papillary-like nuclear features." (PMID 35646190, 2022). "By comparing gene expression in transgenic RET and BRAF(V600E) thyroid tumors, we identified a zebrafish RET gene signature (n = 178 genes)." (PMID 35510953, 2022). "Several studies already described an abundant presence of immune cells in BRAF V600E positive thyroid tumors with more aggressive behavior, as well as higher expression of immune evasion genes such as PD-L1, IDO1, and CTLA-4." (PMID 34680332, 2021). "BRAF (V600E) circulating thyroid tumor DNA can be detected in plasma and is correlated with a final diagnosis of the classical variant of PTC." (PMID 34475951, 2021). "The V600E mutation site of the BRAF gene and the Q61R mutation site of the NRAS gene were highly prevalent in ectoderm-derived skin cancer and endoderm-derived thyroid tumors." (PMID 33308219, 2020). "In this study, we show that CAFs and senescent TC cells co-occur in various histotypes of BRAF-driven thyroid tumors and localize at the tumor invasive front." (PMID 31906302, 2020). "We examined the utility of microfluidic digital PCR (dPCR) for detection of BRAF and TERT mutations in thyroid tumors." (PMID 31810221, 2019). "To determine the BRAF expression pattern in human thyroid tumors, we screened BRAF expression in normal and cancerous thyroid tissues using publically available GENT database." (PMID 30760304, 2019). "Database profiling revealed that thyroid tumors demonstrated increased BRAF expression compared to normal thyroid tumors." (PMID 30760304, 2019).
thyroid tumor (continued). "The primary thyroid tumor, pancreatic metastasis, and cervical lymph node metastasis were both positive for BRAF V600E and TERT promoter (C288T) mutations." (PMID 31781034, 2019). "Inhibition of E-cadherin expression has been described in BRAF-driven thyroid tumors in which the MAPK pathway is activated, but little is known about the mechanisms involved in E-cadherin repression in RAS-driven tumors where PI3K/AKT is activated." (PMID 27384483, 2016). "Our results show a higher prevalence of BRAF mutations and a much lower overall prevalence of RET/PTC and RAS alterations in thyroid tumors as compared to Western reports." (PMID 24591770, 2014). "Because MLH1 promoter methylation was previously associated with MSI and a BRAF V600E mutation, we tested the methylation status of MLH1 in a series of thyroid tumours and correlated them with mutational status and MSI." (PMID 23414134, 2013). "BRAF mutations have been associated with more aggressive and less differentiated papillary tumors, and this is consistent with the inhibition of thyroid-tumor cell growth induced by the blockade of BRAF kinase." (PMID 20628483, 2010). "Among 259 thyroid tumor samples screened, this group demonstrated a 100% correlation in BRAF V600E detection rate between LCPCR and single strand conformational polymorphism." (PMID 16606457, 2006). "In one such study, 52% of thyroid tumor specimens carried clinically relevant mutations in at least one screened gene, most frequently involving KRAS (86%), followed by NRAS (7%), BRAF (6%), and combined NRAS + BRAF mutations (2%)." (PMID 41595518, 2026). "In contrast, in human medicine, the molecular characterization of thyroid tumor-ascertained mutations in BRAF, NRAS, HRAS, and KRAS is relevant as they are players implicated in thyroid tumor progression through their activation of MAPK- and mTOR-signaling pathways." (PMID 40711277, 2025). "The BRAF mutation status was consistent in 18 out of 21 thyroid tumors (positive in 12 cases, negative in 6 cases), and in 12 out of 15 patients, the BRAF status of metastatic lymph nodes matched that of their primary tumors." (PMID 39135992, 2024). "Based on observations of the immunosuppressive microenvironment of advanced thyroid tumors and prior studies of the possible immune-potentiating effects of BRAF inhibitors, several studies have evaluated the efficacy of combined BRAF blockade with immunotherapy." (PMID 38275291, 2024). "The BRAF V600E mutation is solely found in PTC and PTC-derived undifferentiated cancers, and is absent in normal thyroid tissue, thyroid follicles, and other types of thyroid tumors." (PMID 38218832, 2024). "We investigated the differential methylation of genes using 450 K methylation array of paired thyroid tumor and normal tissue from the same individuals with and without BRAF mutation." (PMID 36975440, 2023). "Finally, we tested the use of synthetic histology to augment pathologist-in-training education by creating a cGAN-based educational curriculum illustrating the BRAF-RAS spectrum in thyroid neoplasms." (PMID 37248379, 2023). "Another potential biomarker of thyroid neoplasms is BRAF V600." (PMID 37547301, 2023). "TERT promoter mutations have been found to be associated with the presence of the BRAF-V600E mutations: the coexistence of BRAF-V600E and TERT mutation has been demonstrated to define a particularly aggressive group of thyroid tumors and in particular with tumor recurrence and mortality." (PMID 33572167, 2021). "The BRAF positive thyroid neoplasms follow a typical phenotype-genotype correlation." (PMID 34934597, 2021). "The finding of both a codon 600 BRAF and a C228T TERT promoter mutation in the TCV-PTC arising ectopically in our case mirrors previous observations in high-risk cases of thyroid tumors arising within the thyroid gland, as our patient developed distant metastases 4 years after surgical removal." (PMID 33466206, 2021).
thyroid tumor (continued). "The study aimed to study the AKT / mTOR signaling pathway components, transcriptional and growth factors, as well as steroid hormone receptors and nuclear factors Brn-3α and TRIM16 expression in the tissue of the primary thyroid tumor and metastases, depending on the BRAF- V600E status." (PMID 34319022, 2021). "The pituitary tumor samples revealed no mutations, while among the thyroid tumor samples BRAF (6/14, 42.9%) was the most frequently mutated gene, followed by NRAS (3/11, 27.3%)." (PMID 32333269, 2020). "As validation of the proposed model, they investigated the expression of LOX and COL1A1 genes in human TC by using two public datasets and confirmed their upregulation in thyroid tumors as well as the association with BRAF mutation, but not RAS mutation." (PMID 31906302, 2020). "RET/PTC rearrangements analysis on thyroid tumor has not been extensively performed in Korea, given the prevalence of the BRAF V600E mutation in PTC in Korea." (PMID 28417935, 2017). "Second, whether the Shh pathway is involved in thyroid tumor initiation or facilitates tumor development initiated by oncogenes, such as mutant BRAF, RAS, or RET, needs to be verified in a transgenic mouse model." (PMID 29163356, 2017). "However, it has been shown that thyroid tumor cells, characterized by a constitutive activation of the MAPK pathway (due to the mutations of oncogenes such as RAS, BRAF, and RET/PTC), are more susceptible to NK cell-mediated killing." (PMID 27563819, 2016). "In our cohort of 79 thyroid neoplasms, 20 of 40 PTCs and none of benign nodules harbored BRAF mutation." (PMID 24588959, 2014). "Whether promoter hypermethylation of the MLH1 and MGMT genes is the underlying mechanism associated with presence of BRAF V600E, RAS, IDH1, PIK3CA mutations and/or other genetic alterations found in thyroid tumours is still unknown." (PMID 23414134, 2013). "We successfully used this assay to characterize the frequency of BRAF V600E in thyroid tumors." (PMID 24252159, 2013). "We then analyzed BRAF V600E in thyroid tumors using the ARMS-PCR method." (PMID 24252159, 2013). "Significant findings of our study include new and rare BRAF mutations in malignant and non-malignant thyroid tumors that in cases of T599dup and K601E seem to confer a certain risk for progressive TC." (PMID 22925390, 2012). "Investigations have also linked BRAF mutations to hypermethylation, which may be associated with increased production of vascular endothelial growth factor in BRAF-positive thyroid tumors." (PMID 24281099, 2010). "BRAF is also thought to confer a poorer prognosis compared to sporadic thyroid tumors that do not have the mutation, but for this to be significant in clinical decision-making, more prospective studies need to be done." (PMID 24281099, 2010). "A low prevalence of the BRAF V600E mutation was reported in patients with acromegaly with thyroid neoplasia, which suggests that this mechanism would appear not to be the main cause of the development of thyroid tumors in patients with acromegaly." (PMID 40088375, 2025). "Approximately 70% of TCs have BRAF gene point mutations, and BRAFV600E mutations in PTC patients are associated with invasive tumour phenotypes and increased risk of tumour recurrence, as the early mutations of the driving gene BRAF can alter the epigenetics of thyroid tumour tissue." (PMID 34923978, 2021). "Afirma XA detected many fusions seen in thyroid neoplasms like PAX8::PPARG, ETV6::NTRK3, CCDC6::RET, NCOA4::RET, STRN::ALK, AGK::BRAF, SND1::BRAF and RBPMS::NTRK3." (PMID 37510219, 2023). "Mutations in the intracellular signaling pathways involving RAS, BRAF, and PI3K/Akt play a key role in thyroid tumor cell growth and survival." (PMID 35207709, 2022). "Normally, activation of a tyrosine kinase leads to a cascade of sequential phosphorylation of RAS, BRAF, MEK and then MAPK, so the MAPK/ERK pathways inhibitors have become an important target for thyroid tumors treatment." (PMID 34264510, 2022).
thyroid tumor (continued). "We also tested the role of BRAF V600E and TERT in thyroid tumor growth using the BRAF V600E inhibitor PLX4032 and stable TERT knockdown to suppress the MAPK pathway and the TERT, respectively, in K1 cell, from which xenograft tumors were derived." (PMID 29422527, 2018). "The significance of BRAF mRNA expression in thyroid tumors has been reported previously, and recurrence or distant metastasis in PTC patients has been shown to be related to higher BRAF mRNA expression." (PMID 27410688, 2016). "The rate of the BRAF V600E mutation in patients with PTC ranges from 25–82.3%, whereas it is absent in other types of thyroid tumors." (PMID 38047112, 2023). "Our findings further suggest that tissue microenvironment, possibly involving local interplay of BRAF-mutant and non-mutant cells, modifies thyroid tumor development through the action of estrogen or other sex-related factors." (PMID 34379110, 2022). "SOS1 and SPOP have been previously found mutated in thyroid tumors negative for RAS and BRAF mutations and in several types of cancers such as prostate, lung, and colon." (PMID 34680332, 2021). "The proposed model in which CAFs-TC cells cross-talk promotes the progression from PTC to aggressive PDTC thus requires a specification: this interaction is accordingly observed in human thyroid tumors, both in PTC and aggressive PDTC or ATC, but it appears to be distinctive for BRAF-driven tumors." (PMID 31906302, 2020). "Here we show that HRAS, but not BRAF, induces ß-catenin activation, unveiling a novel mechanism of ß-catenin stabilization in thyroid tumor cells contingent on AKT activity." (PMID 27384483, 2016). "BRAF mutation in PTC can range from 29–83% and exclusively occur as the T1799A transversion mutation in exon 15; the mutations in exon 11 (seen in non-thyroidal tumors) are not seen in thyroid tumors." (PMID 16867191, 2006). "We then asked whether ex vivo addition of a BRAF V600E-specific inhibitor to a tumor lysate could be used to distinguish between BRAF V600E and non-BRAF V600E thyroid tumors, as well as between recurrent and non-recurrent tumors." (PMID 37760447, 2023). "Ex vivo spiking of PTC thyroid tumor lysates with the specific kinase inhibitor dabrafenib achieved partial differential inhibition of somatic BRAF V600E-positive versus non-BRAF V600E thyroid tumors and of recurrent versus non-recurrent tumors, which was not the case with regorafenib and sorafenib." (PMID 37760447, 2023). "We also determined whether dabrafenib (BRAF V600E-specific inhibitor), as well as sorafenib and regorafenib (RAF inhibitors), can differentiate BRAF V600E from non-BRAF V600E thyroid tumors." (PMID 37760447, 2023). "However, due to the high throughput and high cost of the equipment, NGS is not suitable for all thyroid tumors or nodules patients for initial screening, particularly for the detection of a BRAF gene." (PMID 35992139, 2022). "Significantly, no distant metastasis was detected in any patients with BRAF-mutant thyroid tumors." (PMID 35015563, 2022). "Based on gene expression profiles, thyroid tumors were classified as three molecular subtypes regardless of histological subtypes, BRAF–like, RAS–like, and Non–BRAF–Non–RAS." (PMID 27494611, 2016). "Second, we investigated whether the BRAF V600E-specific inhibitor dabrafenib, as well as the RAF inhibitors sorafenib and regorafenib, induce differences in kinase inhibition between BRAF V600E and non-BRAF V600E thyroid tumors, and between recurrent and non-recurrent tumors." (PMID 37760447, 2023). "Importantly, subsequent analyses are warranted in order to assess whether the magnitude of the observed clinical response to BRAF and MAP2K inhibitors in the respective studies is correlated with the degree of autophagy activity in responding and nonresponding thyroid tumors." (PMID 27105307, 2016).
ovarian carcinoma (116 papers, 2005 to 2025). A malignant neoplasm originating from the surface ovarian epithelium. "Two patients (6%) had partial response: one with uterine cervical cancer on atezolizumab based on TMB 12 mutations/Mb, and one with ovarian cancer on cobimetinib based on a BRAF V600E mutation." (PMID 40468525, 2025). "This review also addresses the paradoxical better prognosis linked to KRAS and BRAF mutations in ovarian cancer." (PMID 38391958, 2024). "Though frequencies are low, BRAF mutations have also been reported in both breast cancer and ovarian cancer." (PMID 38539548, 2024). "Deleterious mutations resulting in BRAF activation were also found in 0.6–1% of lung, pancreatic, thyroid, and ovarian cancers." (PMID 38539548, 2024). "Lavages, however, carried mutations in other BRAF hotspot codons common in ovarian cancer albeit at much lower frequency (codons 594, 581, and 597, representing 2.9%, 2.2%, and 2.2% of BRAF mutations, respectively)." (PMID 36311816, 2022). "One of the histological and molecular subtypes of ovarian cancer is low-grade serous (LGS) ovarian carcinoma characterized by BRAF, KRAS, NRAS and ERBB2 mutation, amplification or overexpression." (PMID 25408231, 2014). "We reported earlier that KRAS or BRAF mutations were quite common in low-grade serous ovarian carcinomas with prototypic histology of type I ovarian carcinoma but rare in high-grade serous ovarian carcinomas." (PMID 23820584, 2013). "In fact, other mechanisms have been suggested in other types of tumors, as CHD5 mutation or methylation is associated with KRAS or BRAF mutation in ovarian cancer, and CHD5 expression correlates with MYCN amplification in neuroblastoma." (PMID 22569290, 2012). "Somatic mutations in the oncogenes KRAS or BRAF usually occur as mutually exclusive events in epithelial ovarian cancer, have been reported in borderline ovarian serous carcinomas or low-grade ovarian serous carcinomas, and occur at a low frequency in HGSCs." (PMID 23029043, 2012). "In light of our in vivo and in vitro findings, we propose that ovarian cancer patients with KRAS or BRAF mutations be considered for MEK inhibitor (CI-1040) therapy if they recur after conventional platinum and taxane chemotherapy." (PMID 19018267, 2008). "Somatic mutations of either KRAS or BRAF were identified in 12 (20.6%) out of 58 ovarian carcinomas." (PMID 19018267, 2008). "Profound growth inhibition and apoptosis were observed in CI-1040-treated cancer cells with mutations in either KRAS or BRAF in comparison with the ovarian cancer cells containing wild-type sequences." (PMID 19018267, 2008). "Next, to clarify the roles of ERK1/2 activation in ovarian cancers harbouring KRAS or BRAF mutations, we inactivated ERK1/2 in ovarian cancer cells using CI-1040." (PMID 19018267, 2008). "Ovarian carcinomas with mutations in either KRAS or BRAF were more sensitive to growth inhibition and apoptosis induction by the MEK inhibitor, CI-1040." (PMID 19018267, 2008). "The findings in this study indicate that an activated ERK1/2 pathway is critical to tumour growth and survival of ovarian cancers with KRAS or BRAF mutations." (PMID 19018267, 2008). "Ovarian carcinomas with KRAS or BRAF mutation are clinically low-grade carcinomas of serous or other histological subtypes that are often refractory to conventional cytotoxic chemotherapy." (PMID 19018267, 2008). "Bidirectional sequencing of all the coding exons of BRAF in 15 well-characterized and highly utilized ovarian cancer cell lines identified four cell lines with BRAF mutations." (PMID 18060073, 2007).